GDF15 (growth differentiation factor 15)
Diseases named in the same sentence as GDF15 in open-access papers (continued):
Sharing a sentence is not in itself a finding about the gene and the disease.
cancer (continued). "It was the first study to assess the associations between combinations of biomarkers linked to biological ageing (GDF-15, NT-proBNP, HbA1C, CRP, cystatin-C) and cancer risk." (PMID 34935094, 2022). "GDF15, which is overexpressed in various malignancies, including PCa, is a potential serum marker in different types of cancers and contributes to tumor development and metastasis." (PMID 35058441, 2022). "GDF-15 plays diverse roles under physiological and pathological conditions in relation to inflammation, metabolism and cancer." (PMID 36008442, 2022). "Increased GDF15 levels have been reported under various disease conditions, including cancer, cardiovascular disease, liver and kidney diseases, and with inflammation, age, smoking, stress, and tissue injury." (PMID 35160195, 2022). "Stress-responsive cytokine GDF15 and its receptor GDNF receptor alpha like (GFRAL) have been implicated in cancer cachexia." (PMID 35994202, 2022). "Together, these results confirmed that GDF-15, possibly as an active component in exosomes, was involved in the development of muscle atrophy in cancer cachexia." (PMID 35379793, 2022). "Several studies have correlated high levels of GDF-15 with the development of cancer-related anorexia and cachexia, as well as worse survival." (PMID 35872912, 2022). "Different cellular stresses induce the expression of GDF15 to mitigate different acute insults including infection, injuries and cancer chemotherapy." (PMID 35626166, 2022). "We found that GDF15 was higher in cancer patients receiving platinum-based chemotherapy and is positively associated with weight loss, supporting its role in mediating platinum-induced side-effects of emesis, nausea, and weight loss." (PMID 35406637, 2022). "Further study is necessary to clarify the pathophysiological roles of GDF15 and try to develop drugs targeting GDF15 for the treatment of diseases such as cancer cachexia." (PMID 35379793, 2022). "GDF-15 can have opposite effects in different cancer cell lines, and has been shown to inhibit cell growth, to activate apoptosis, and to increase cancer invasiveness." (PMID 36230513, 2022). "In elderly men, GDF-15 levels aid to better predict cardiovascular outcome as well as cancer mortality and morbidity." (PMID 36361969, 2022). "Different studies have shown higher expression of GDF15 mRNA and protein in cancer biopsies compared to their corresponding normal tissues." (PMID 35626166, 2022). "Recently, several studies have demonstrated the close links between GDF15 and the development of cancers." (PMID 34697897, 2022). "Although the tumor-suppressive effects of GDF15 have occasionally been reported, especially concerning its pro-apoptotic activity in some cancer cells, the vast majority of results support a tumor-promoting role for GDF15." (PMID 35694408, 2022). "GDF15 strongly correlates with many health problems such as obesity, diabetes, cardiovascular disease, and cancers, hence, is a potential indicator of disease progression." (PMID 34662721, 2022). "This study allowed us to have an umbrella view of the associations between five biomarkers linked to biological ageing (GDF-15, NT-proBNP, HbA1C, CRP, cystatin-C) and cancer and CVD risks." (PMID 34935094, 2022). "In cancer, GDF15 is elevated in the advanced stages of several cancer types, where it participates in the induction of cachexia affecting patients with late-stage cancer." (PMID 35626166, 2022). "On the other hand, GDF-15 also acts on immune cells and promotes cancer progression by immune escape." (PMID 35508696, 2022). "The cut-off level to characterize a high serum level of GDF-15 in APC thus should discriminate cancer-related upregulation of GDF-15 from the effects of benign pancreatic disease." (PMID 34638326, 2021).
cancer (continued). "It has long been known that circulating GDF15 levels correlate with lower BMI and cachexia in patients with cancer, heart failure, or chronic kidney disease." (PMID 33903632, 2021). "GDF15, a recently identified cachexia-inducing factor, was shown to be a promising target for treating cancer cachexia." (PMID 33925872, 2021). "In patients, we observed a trend to elevated circulating GDF15 levels in weight losing (Ccx) vs. weight stable cancer (WSC) patients." (PMID 35008253, 2021). "For example, 1,25(OH)2D3 suppresses proliferation by inducing microRNA-627, which subsequently targets JMJD1A and suppresses the expression of cancer-promoting genes such as GDF15." (PMID 34867333, 2021). "Herein, we critically review the mechanisms involving GDF15 in cancer cachexia and discuss therapeutic interventions to improve outcomes in people living with cancer." (PMID 33442410, 2021). "GDF15 induces cancer cachexia via its action on the hypothalamus to decrease appetite and elicits a lipolytic response in adipose tissue." (PMID 33925872, 2021). "GDF15, also known as NSAID-activated gene-1 (NAG-1), has been implicated in numerous biological processes and diseases, including energy homeostasis, cancer, inflammation, cardiovascular diseases, and obesity." (PMID 33850096, 2021). "Death rates for cancer in the upper tertile of GDF-15 and IGFBP7 were 11.5% and 9.7%, compared to 3.9% and 6.0% in the lower tertile (p < 0.0001 and p = 0.011, respectively)." (PMID 34217226, 2021). "We used ENCORI and TIMER analysis and revealed that miR-216a and GDF15 expression status varied in different cancers." (PMID 34948431, 2021). "GDF-15 levels in various cancers should thus be assessed in concert with the ratio of metastasis in the study population." (PMID 34638326, 2021). "In inflammatory conditions, cardiovascular diseases, and cancer, GDF15 is a biomarker for disease outcome." (PMID 33442410, 2021). "IL6 and GDF15 are important mediators of cancer cachexia with therapeutic relevance, since blocking either IL6 or GDF15 resulted in improved disease outcomes in cachectic animals." (PMID 35008253, 2021). "Elevated GDF15 mRNA and protein levels have been reported in cancer biopsies, suggesting a pro-tumorigenic role for GDF15." (PMID 33850096, 2021). "GDF15 (also known as macrophage inhibitory cytokine-1, MIC-1) is upregulated by various stresses and has been associated with inflammation, cancer, and cardiovascular disease." (PMID 33681189, 2021). "ErbB2, which is implicated in cell proliferation, migration, and differentiation, is transactivated by GDF15 in human cancer cells." (PMID 34445593, 2021). "More recently, also circulating growth/differentiation factor-15 (GDF15) has been identified as a prominent cachexia biomarker correlating with reduced survival in cancer patients." (PMID 35008253, 2021). "Overall, reports of GDF15-dependent effects in cancer are context-dependent and mainly studied in animal models." (PMID 33442410, 2021). "GDF15 has been linked to cancer cachexia and a recent study found that inhibition of the GDF15-GFRAL activity by a GFRAL targeting antibody reversed cancer cachexia in mice." (PMID 33464381, 2021). "It has been shown than GDF15 promoted cancer stemness, and inhibition of GDF15 sensitised cells to IR." (PMID 33069104, 2021). "While the tissue source of GDF15 is quite obvious in cancer and pregnancy, it is less obvious for exercise." (PMID 34831213, 2021). "It is a member of the TGF-β superfamily, and GDF15 expression was demonstrated for various human cancers." (PMID 34638458, 2021). "In our cohort, the GDF15 positivity rate more frequently occurred in the well differentiated cancer cells (100.00%) than in the moderately (77.78%) and the poorly differentiated ones (61.40%)." (PMID 34149933, 2021). "GDF15 has been linked to cancer cachexia and inhibition of GDF15–GFRAL activity by a GFRAL targeting antibody reversed cancer cachexia in mice." (PMID 34831213, 2021).
cancer (continued). "GDF15 is highly expressed in prostate CAFs and fibroblast-derived GDF15 exerts paracrine effects on cancer cell migration, invasion and tumor growth." (PMID 34681633, 2021). "Given the very limited tissue distribution of GFRAL, direct effects of GDF-15 on cancer or immune cells are likely to be mediated via GFRAL-independent signaling pathways." (PMID 32508832, 2020). "Overexpression of RNPC1 in various cancer cell lines upregulated GDF15 mRNA and protein and prolonged the GDF15 mRNA half-life." (PMID 32310257, 2020). "In contrast, the increased expression and secretion of GDF15 promote cancer development by regulating cell proliferation, immune response, angiogenesis, infiltration and metastasis." (PMID 33098235, 2020). "In a large-scale screening, GDF-15 was the most prominently overexpressed soluble factor across a large range of cancer types." (PMID 32508832, 2020). "GDF15 expression increases during pathological states including inflammation, aging, smoking, cancer, oxidative stress, and hypoxia." (PMID 33344478, 2020). "When GDF15 is produced in excess, for example in cancer, it can have a profound effect on appetite and weight regulation." (PMID 32310257, 2020). "As a divergent member of the TGF-β superfamily, GDF15 is considered to be a promoter for the development and progression of some cancers." (PMID 33123476, 2020). "Both cancer groups showed GDF-15 serum levels higher compared to controls (p = 0.00006; p = 0.008, respectively)." (PMID 33396237, 2020). "One major pathway regulating GDF-15 in myocytes, hepatocytes and cancer cells is the endoplasmic reticulum (ER) stress." (PMID 33302552, 2020). "On the one hand, it is highly likely that elevated levels of GDF15 actively participate in driving nausea, emesis, and cachexia syndromes in the context of cytotoxic chemotherapy, cancer, and other severe systemic diseases." (PMID 32310257, 2020). "Reports on GDF-15-dependent effects in cancer cells are numerous, but the range of reported effects is complex, diverse, and inconsistent, with no consensus in sight." (PMID 32508832, 2020). "Correlation between GDF-15 serum and/or tumor levels with clinical outcome in different cancer types." (PMID 32508832, 2020). "Growth Differentiation Factor-15 (GDF15) is a divergent TGF-beta superfamily cytokine that is overexpressed by most cancers and is induced by anticancer therapy." (PMID 32502202, 2020). "Especially in cancer, GDF15 is sometimes secreted in an unprocessed form with its propeptide still attached." (PMID 32502202, 2020). "GDF15 has been demonstrated to play multiple roles in various pathological conditions such as cancer, inflammatory diseases, cardiovascular diseases, lung diseases, kidney injury, and metabolic disorders." (PMID 33178828, 2020). "The role of GDF15 in the biology of cancer has been studied using a number of different approaches, which have yielded somewhat contradictory results." (PMID 32502202, 2020). "Using this OTTEM model, we can demonstrate similar GDF15 mediated, adaptive immunity dependent changes in tumor development, as that seen using spontaneous cancer development in TRAMP and TRAMPfmsmic mice." (PMID 32502202, 2020). "Although GDF15 is regarded as one of the best biomarkers for the diagnosis of malignant tumors, its biological roles in tumors need to be further studied." (PMID 33098235, 2020). "This review aims to summarize the physiological and pathophysiological functions of GDF-15, with a main focus on its role in cancer and cancer immunotherapy." (PMID 32508832, 2020). "In a community-dwelling cohort of younger urban adults (mean age 49.6) with diverse racial and socioeconomic status, we found that elevated serum GDF15 level was strongly associated with all-cause mortality, CVD- and cancer-specific mortality risk." (PMID 32764826, 2020). "GDF15 is overexpressed by the majority of cancers and its serum levels rise broadly in line with stage and extent of disease." (PMID 32502202, 2020).
cancer (continued). "Overall, there are numerous options for exploring the potential of GDF-15 inhibitors in cancer immunotherapy." (PMID 32508832, 2020). "Findings from these studies indicate that GDF-15 is a promising prognostic marker for identifying cancer manifestation and progression." (PMID 32508832, 2020). "The metabolic functions of GDF15 were first discovered when human GDF15 was overexpressed in mice to investigate its role in cancer progression." (PMID 32372975, 2020). "Cancer cells, via the release of soluble factors such as hormone-sensitive lipase and growth differentiation factor 15 (GDF15), promote the release of FAs from neighboring adipocytes." (PMID 33339398, 2020). "The GDF-15 serum levels (pg/mL) were significantly higher in cancer patients (median 6.84, IQR 6.61; 7.32) with respect to controls (median 6.31, IQR 6.09; 6.73) (p = 0.00016)." (PMID 33396237, 2020). "The mechanisms of action of GDF-15 in cancer should be further clarified also regarding the changes in muscularity." (PMID 33396237, 2020). "A number of tumor xenograft studies have been used to examine the role of GDF15 in cancer; however, the results have been less consistent." (PMID 32310257, 2020). "More studies are needed to fully clarify the functions and mechanisms of GDF15 in tumor progression, especially in regulating cellular metabolism of cancers." (PMID 32076610, 2020). "Overall, the role of GDF-15 in the tumor microenvironment as currently understood, leads to reasonably consistent explanations for the experimental and epidemiological findings on GDF-15 in cancer." (PMID 32508832, 2020). "Cytokine and hormonal profiling at the transcript and protein level demonstrated GDF15 to be one of the most upregulated factors measured in various mouse models of cancer cachexia." (PMID 32310257, 2020). "GDF15 serum levels are known to be elevated in many disease processes that course with cellular stress, most prominently cancer and cardiovascular diseases." (PMID 32424099, 2020). "In this light, our results indicate a negative correlation, although weak, between FAACT score and GDF-15 levels in our cohort of cancer patients." (PMID 33396237, 2020). "GDF15 has been reported to have multiple functions in various pathologies, including inflammation, cancer, cardiovascular diseases, and obesity." (PMID 32076610, 2020). "Elevated expression of GDF-15 has been demonstrated in different types of cancer including breast, colorectal, prostate, and head and neck, among others." (PMID 33419237, 2020). "Accumulating evidence, largely from animal models, suggests that during early stages of chronic inflammation, cancer and metabolic disorders, the effects of GDF15 are aimed at limiting disease process." (PMID 32764826, 2020). "GDF15 is known to regulate nausea and vomiting and its inhibition slows cachexia in preclinical cancer models." (PMID 33334063, 2020). "In the present work, we show that elimination of RSU-1 from two BC cell lines impairs cancer cell invasion which is completely reversed by GDF-15 treatment." (PMID 30621163, 2019). "GDF15 is also highly expressed in malignant tumor and promote tumorigenesis and immunosuppression, consistent its function in regulating a neuroimmune-modulatory circuit." (PMID 31222070, 2019).
cancer (continued). "Although, there are many studies documenting the role of GDF-15 on proliferation, invasion and migration of cancer cells, these results are contradictory tending to indicate that its function is, to a certain extent, cell type-specific." (PMID 31412547, 2019). "For example, GDF15 plays a role in cancer cachexia, mitochondrial diseases, and as a mediator of intensive care unit (ICU)‐acquired muscle weakness." (PMID 30924297, 2019). "In gynecological malignancies GDF-15 is reportedly an independent marker of aggressive disease in ovarian cancer." (PMID 30645608, 2019). "GDF-15 has also been found to be upregulated in many cancer types, and it is even detected in the plasma of cancer patients." (PMID 30621163, 2019). "This study aimed to explore the relation of GDF‐15 to other cardiac biomarkers and the general association of GDF‐15 on prognosis in an unselected cohort of treatment‐naïve cancer patients." (PMID 31463975, 2019). "Growth Differentiation Factor-15 (GDF-15) is another molecule connecting actin cytoskeleton reorganization, mechanical compression and cancer." (PMID 30621163, 2019). "It has previously been reported that serum GDF-15 levels progressively increase from premalignant colonic lesions to cancer initiation with a further increase of plasma levels GDF-15 at time of metastasis." (PMID 30645608, 2019). "We found that RSU-1 silencing downregulates GDF-15, and inhibits cancer cell invasion, a phenomenon which is completely reversed by treatment of cells with human recombinant GDF-15 (hrGDF-15)." (PMID 30621163, 2019). "The prognostic value of GDF-15 is previously explored in cardiac disease, during pregnancy and in cancer." (PMID 30645608, 2019). "It has been suggested that GDF-15 suppresses immune cells such as macrophages by suppressing the release of certain cytokines and enhances cancer cell growth." (PMID 30646851, 2019). "GDF-15 can have an affect on invasion by using other pathways as demonstrated in experiments using other cancers." (PMID 29467963, 2018). "Subsequent studies found that increased expression and high circulating levels of GDF15 acted as a critical driver of cancer cachexia, largely by decreasing appetite." (PMID 30687235, 2018). "It has been reported that GDF15 induced a significant ERK activation in the malignant progression of human cancer cell." (PMID 29566722, 2018). "Studies have shown that similar to other TGF-β family members, GDF15 is involved in the inhibition of cell growth, induction of apoptosis, and enhancement of cancer invasiveness in different cancer cell lines." (PMID 29566722, 2018). "A functional role for GDF15 has been suggested in cancer, cardiovascular disease, kidney disease and metabolic disease." (PMID 30542297, 2018). "Recently, it was found that expression of growth differentiation factor-15 (GDF-15) in conjunction with other inflammatory markers is upregulated by oxidative stress, tissue ischemia, and cancer in organ tissues, including the heart and kidneys." (PMID 29682097, 2018). "All of these data are in accordance with each other and support the idea that GDF15 is a tumor promoter in several human cancers." (PMID 29636108, 2018). "Along the same line, increased circulating levels of tumor necrosis factor α (TNFα), interleukin-6 (IL-6), γ-interferon (INF), and, more recently, growth and differentiation factor 15 (GDF15) have been reported in cachectic cancer patients." (PMID 29785246, 2018). "It is also notable that abnormal overproduction of GDF15 in cancer was recently found to be the key driver of cancer anorexia and cachexia which, like HG, exhibits symptoms of chronic nausea and weight loss." (PMID 29563502, 2018). "In response to multiple cellular stressors, such as acute injury, inflammation, and cancer, GDF15 expression can be dramatically induced." (PMID 29967567, 2018). "Subsequently, Kdm3a upregulates the expression of VEGF, adrenomedulin and GDF15 to promote cancer cell growth." (PMID 29156681, 2017).